EFL1 (elongation factor like GTPase 1)
Description:
GTPase involved in the biogenesis of the 60S ribosomal subunit and translational activation of ribosomes. Together with SBDS, triggers the GTP-dependent release of EIF6 from 60S pre-ribosomes in the cytoplasm, thereby activating ribosomes for translation competence by allowing 80S ribosome assembly and facilitating EIF6 recycling to the nucleus, where it is required for 60S rRNA processing and nuclear export.
Synonyms: EFTUD1; FAM42A; FLJ13119; HsT19294; RIA1; SDS2
Tractability: PROTAC: ubiquitination databases record sites on it.
Gene: Protein-coding gene on chromosome 15 (82,130,206 to 82,262,773, reverse strand). Ensembl gene ENSG00000140598.
Subcellular location (Human Protein Atlas): Cytosol
Gene Ontology:
Molecular function: GTPase activity; protein binding; ribosome binding; GTP binding
Biological process: cytosolic ribosome assembly; GTP metabolic process
Cellular component: cytosol; ribonucleoprotein complex
Genetic constraint (gnomAD): Loss-of-function variants: 70 observed, 118.89 expected, observed/expected ratio (o/e) 0.59, 90% interval 0.49 to 0.72. The upper end of that interval is the gene's LOEUF score, 0.72, which puts it in group 2 of 6, group 1 being the genes least tolerant of losing a copy. Missense variants: 1,084 observed, 1,316 expected, observed/expected ratio (o/e) 0.82, 90% interval 0.78 to 0.87. Synonymous variants: 395 observed, 438.83 expected, observed/expected ratio (o/e) 0.9, 90% interval 0.83 to 0.98.
Gene-disease validity (ClinGen):
ClinGen rates the evidence that EFL1 causes each of these diseases.
Shwachman-Diamond syndrome 2 (autosomal recessive): Definitive. Shwachman-Diamond syndrome-2 (SDS2) is characterized by exocrine pancreatic dysfunction, hematopoietic abnormalities, short stature, and metaphyseal dysplasia ({1:Stepensky et al., 2017}).nnFor a discussion of genetic heterogeneity of Shwachman-Diamond syndrome, see SDS1 (OMIM:260400).
Homologues: Orthologues: chimpanzee EFL1 (99% identical), macaque EFL1 (98% identical), pig EFL1 (93% identical), guinea pig EFL1 (91% identical), mouse Efl1 (91% identical), rat Efl1 (91% identical), dog EFL1 (88% identical), rabbit EFL1 (87% identical), tropical clawed frog efl1 (76% identical), zebrafish efl1 (71% identical), Drosophila melanogaster CG33158 (44% identical), Caenorhabditis elegans K10C3.5 (31% identical). Paralogues in human: EEF2 (29% identical), EFTUD2 (24% identical), GFM1 (15% identical), GFM2 (15% identical), GUF1 (15% identical), EEF1A1 (10% identical), EEF1A2 (10% identical), MTIF2 (9% identical), EEFSEC (9% identical), HBS1L (8% identical), TUFM (8% identical), EIF5B (8% identical), and 6 more.
Diseases named in the same sentence as EFL1 in open-access papers:
EFL1 is named in the same sentence as 21 diseases in open-access papers, as found by Europe PMC text mining. Sharing a sentence is not in itself a finding about the gene and the disease. The quoted sentences say what the papers report.
Shwachman-Diamond syndrome (7 papers, 2018 to 2024). "Different EFL1 variants can contribute to a broad spectrum of symptoms that overlap with those observed in Shwachman-Diamond syndrome." (PMID 39543639, 2024). "Recently, mutations in EFL1 together with those in SBDS have been described to cause Shwachman–Diamond Syndrome." (PMID 36009035, 2022). "Functional analysis of patient‐derived B‐lymphoblastoid and SV40‐transformed fibroblast cell lines suggests that the compound heterozygous EFL1 variants impaired mature ribosome formation leading to compromised protein synthesis, ultimately resulting in a severe form of Shwachman–Diamond syndrome." (PMID 39379149, 2024). "However, subsequent reanalysis of her ES data through the UDN demonstrated homozygosity for a EFL1 p.Thr127Ala missense pathogenic variant, which was thought to explain her Shwachman-Diamond syndrome-like phenotype (OMIM #260,400)." (PMID 39543639, 2024). "The release factors SBDS and EFL1—both mutated in the leukemia predisposition disorder Shwachman-Diamond syndrome — license entry of nascent 60S ribosomal subunits into active translation by evicting the anti-association factor eIF6 from the 60S intersubunit face." (PMID 35322020, 2022). "The Shwachman-Diamond Syndrome (SDS) is a disorder arising from mutations in the genes encoding for the Shwachman-Bodian-Diamond Syndrome (SBDS) protein and the GTPase known as Elongation Factor Like-1 (EFL1)." (PMID 30545121, 2018).
brain tumor (2 papers, 2013 to 2020). "Increased concentrations of EFL1 were associated with a significant increase in the anti-proliferative activities of free-EFL1 in C6 cells, thus indicating that EFL1 has anti-cancer effects in this type of brain tumor." (PMID 33194638, 2020).
breast carcinoma (2 papers, 2021 to 2023). "Ascites proinflammatory cytokines IL-1β, IL-6, TNF-α were increased in model mice, but were significantly reduced following EFL1 or DOX administration, which demonstrates that EFL1 is able to decrease the generation of proinflammatory cytokines caused by breast cancer liver metastasis." (PMID 37709489, 2023). "In the present study, we performed breast cancer-surgical hepatic implantation (SHI) in female BALB/c mice to assess the effect of EFL1 on breast cancer liver metastasis and explored the potential mechanism." (PMID 37709489, 2023). "This study revealed the suppression effect of EFL1 on breast cancer liver metastasis, and highlights the potential role of inhibiting DDR1 in treating breast cancer." (PMID 37709489, 2023). "Together, these data suggested that DDR1 inhibition is required for EFL1 treating breast cancer liver metastasis." (PMID 37709489, 2023). "We first determined if EFL1 prevents breast cancer liver metastasis using breast cancer (4T1 cell line)-surgical hepatic implantation (SHI) murine models." (PMID 37709489, 2023). "Together, our findings suggested that EFL1 protects against breast cancer liver metastasis in vivo by targeting DDR1-mediated immune infiltration." (PMID 37709489, 2023). "In conclusion, our results suggest that EFL1 protects against breast cancer liver metastasis through targeting DDR1-regulated immune infiltration." (PMID 37709489, 2023). "In our work, EFL1 reduced liver metastasis and mesenteric re-metastasis of breast cancer cells, enhanced liver function and mitigated ascites in breast cancer SHI mice, reflecting the potential of EFL1 in treating breast cancer liver metastasis." (PMID 37709489, 2023). "This suggested that DDR1-regulated immune infiltration was involved in the inhibitory effect of EFL1 in breast cancer liver metastasis." (PMID 37709489, 2023). "In this study, we explored the effect and mechanism of EFL1 on breast cancer liver metastasis." (PMID 37709489, 2023). "We then explored whether EFL1 represses breast cancer liver metastasis by targeting DDR1-regulated immune infiltration." (PMID 37709489, 2023). "However, the effect of EFL1 on breast cancer remains unclear." (PMID 37709489, 2023). "However, the function of EFL1 on breast cancer is not clear." (PMID 37709489, 2023).
brain glioma (1 paper, 2020). A malignant glioma that involves the brain. "The results showed that dual-targeting EFL1-loaded DWSW/NGR-RBCNPs have significant potential as a nanotherapeutic tool for the treatment of brain glioma." (PMID 33194638, 2020).
colon adenocarcinoma (1 paper, 2022). "The objective of this study was to evaluate the transcriptome and miRNA profiles of human colon adenocarcinoma Caco-2 cells in response to Euphorbia factors L1 (EFL1) and EFL2." (PMID 36296525, 2022).
glioma (1 paper, 2020). A benign or malignant brain and spinal cord tumor that arises from glial cells (astrocytes, oligodendrocytes, ependymal cells). "The efficacy of these dual-modified RBCNPs (DWSW/NGR-RBCNPs) following EFL1 encapsulation with respect to glioma treatment was evaluated using both in vitro and in vivo approaches." (PMID 33194638, 2020). "The data showed that EFL1-loaded DWSW/NGR-RBCNPs were the most effective preparation for the treatment of gliomas." (PMID 33194638, 2020). "EFL1-loaded DWSW/NGR-RBCNPs significantly improved the efficacy of anti-glioma treatment both in vitro and in vivo." (PMID 33194638, 2020). "The current results indicate that EFL1-loaded RBCNPs with dual ligand functionalization could significantly improve the treatment efficacy for glioma." (PMID 33194638, 2020). "Results showed that the DWSW peptide-modified nanoparticles could cross the BBB in the in vitro model and that the EFL1 drug could be delivered to C6 glioma cells." (PMID 33194638, 2020).
cancer (2 papers, 2019 to 2020). A tumor composed of atypical neoplastic, often pleomorphic cells that invade other tissues. "Inhibition of eEF2 is toxic to mammalian cells due to inhibition of translation, but here, we demonstrate that inhibition of LSG1, and possibly EFL1 by extension, may provide an effective prosenescent cancer therapy with lesser side effects since translation remains unimpaired." (PMID 31148378, 2019).
tumor (2 papers, 2020 to 2023). "As expected, DDR1 overexpression compromised EFL1-induced pharmacological effects on liver dysfunction, ascites, body weight, tumor weight, tumor volume and tumor morphology." (PMID 37709489, 2023). "In this study, we developed functional targeted EFL1 nanoparticles in order to deliver drugs to tumor tissue." (PMID 33194638, 2020). "Mechanism study revealed that EFL1 intervention enhanced the ratios of CD4+ and CD8+ and CD49b+(NK) T lymphocytes and decreased Treg cells through downregulating DDR1 in the tumor of SHI mice." (PMID 37709489, 2023). "However, EFL1 or DOX intervention further reduced body weight and increased tumor weight and volume, which might be related to the inhibition of ascites and solid tumor metastasis in SHI mice after EFL1 or DOX intervention." (PMID 37709489, 2023).
EFL1 also shares sentences with these, for which no sentence is quoted: abortion (1 paper); bone marrow failure syndrome (1); brain diseases (1); breast tumors (1); cognitive decline (1); developmental delay (1); E. coli infections (1); hematologic malignancies (1); pancreatic insufficiency (1); Shwachman-Diamond syndrome 2 (1); T-cell acute lymphoblastic leukaemia (1); Tics (1); Urinary incontinence (1).